MAP1LC3B (microtubule associated protein 1 light chain 3 beta)
Description:
Ubiquitin-like modifier involved in formation of autophagosomal vacuoles (autophagosomes). Plays a role in mitophagy which contributes to regulate mitochondrial quantity and quality by eliminating the mitochondria to a basal level to fulfill cellular energy requirements and preventing excess ROS production. In response to cellular stress and upon mitochondria fission, binds C-18 ceramides and anchors autophagolysosomes to outer mitochondrial membranes to eliminate damaged mitochondria. While LC3s are involved in elongation of the phagophore membrane, the GABARAP/GATE-16 subfamily is essential for a later stage in autophagosome maturation. Promotes primary ciliogenesis by removing OFD1 from centriolar satellites via the autophagic pathway. Through its interaction with the reticulophagy receptor TEX264, participates in the remodeling of subdomains of the endoplasmic reticulum into autophagosomes upon nutrient stress, which then fuse with lysosomes for endoplasmic reticulum turnover. Upon nutrient stress, directly recruits cofactor JMY to the phagophore membrane surfaces and promotes JMY's actin nucleation activity and autophagosome biogenesis during autophagy.
Synonyms: ATG8F; LC3B; MAP1A/1BLC3; MAP1LC3B-a
Tractability: Small molecule: a structure with a bound ligand is known; it has a high-quality binding pocket. PROTAC: UniProt records ubiquitination sites on it; ubiquitination databases record sites on it; its protein half-life has been measured; a small molecule that binds it is known.
Gene: Protein-coding gene on chromosome 16 (87,383,953 to 87,405,090, forward strand). Ensembl gene ENSG00000140941.
Subcellular location: Cytoplasmic vesicle, autophagosome membrane; Endomembrane system; Mitochondrion membrane; Cytoplasm, cytoskeleton; Cytoplasmic vesicle
Subcellular location (Human Protein Atlas): Vesicles; Basal body; Cytosol
Pathways (Reactome):
Autophagy: Macroautophagy; PINK1-PRKN Mediated Mitophagy; Pexophagy; Receptor Mediated Mitophagy
Disease: Dengue Virus Genome Translation and Replication; SARS-CoV-2 modulates autophagy; Translation of Replicase and Assembly of the Replication Transcription Complex
Cellular responses to stimuli: KEAP1-NFE2L2 pathway
Vesicle-mediated transport: TBC/RABGAPs
Gene Ontology:
Molecular function: ceramide binding; phosphatidylethanolamine binding; protein binding; ubiquitin protein ligase binding; microtubule binding; phospholipid binding
Biological process: autophagosome assembly; autophagosome maturation; autophagy; cellular response to starvation; macroautophagy; mitophagy; cellular response to nitrogen starvation; autophagy of mitochondrion
Cellular component: autophagosome; autophagosome membrane; cytoplasmic vesicle; endomembrane system; mitochondrial membrane; mitochondrion; axoneme; cytosol; extracellular exosome; organelle membrane; cytoskeleton; membrane
Genetic constraint (gnomAD): Loss-of-function variants: 11 observed, 14.68 expected, observed/expected ratio (o/e) 0.75, 90% interval 0.47 to 1.24. The upper end of that interval is the gene's LOEUF score, 1.24, which puts it in group 5 of 6, group 1 being the genes least tolerant of losing a copy. Missense variants: 155 observed, 148.71 expected, observed/expected ratio (o/e) 1.04, 90% interval 0.91 to 1.19. Synonymous variants: 63 observed, 52.05 expected, observed/expected ratio (o/e) 1.21, 90% interval 0.99 to 1.49.
Homologues: Orthologues: chimpanzee MAP1LC3B (100% identical), macaque MAP1LC3B (100% identical), pig MAP1LC3B (99% identical), guinea pig Map1lc3b (96% identical), zebrafish map1lc3b (91% identical), tropical clawed frog map1lc3b (86% identical), Caenorhabditis elegans lgg-2 (55% identical). Paralogues in human: MAP1LC3B2 (99% identical), MAP1LC3A (79% identical), MAP1LC3C (54% identical), GABARAPL2 (38% identical), GABARAP (31% identical), GABARAPL1 (30% identical).
Diseases named in the same sentence as MAP1LC3B in open-access papers:
MAP1LC3B is named in the same sentence as 274 diseases in open-access papers, as found by Europe PMC text mining. Sharing a sentence is not in itself a finding about the gene and the disease. The quoted sentences say what the papers report.
breast carcinoma (86 papers, 2011 to 2026). "Increased MAP1LC3B puncta is also associated with a poor prognosis in several other cancer types, such as breast cancer and oral cancer." (PMID 30477228, 2018). "First, we employed standard MAP1LC3B/LC3B-based autophagy assays as these have been used successfully to monitor autophagy in breast cancer cell lines, including in SKBR3 lines, and under similar stress conditions we employed." (PMID 39982959, 2025). "The accumulated MAP1LC3B and SQSTM1 caused by autophagy inhibition increased chemosensitivity to cancer drugs (CIS and PTX) in breast cancer cell lines." (PMID 34829743, 2021). "Taken together, these results indicate that accumulated MAP1LC3B and SQSTM1 caused by autophagy inhibition might be involved in the chemoresistance of breast cancer cell lines." (PMID 34829743, 2021). "This supports that autophagy promotion by upregulation of ATG12 and MAP1LC3B might cause treatment resistance of ERBB2-positive breast cancer, leading to a worse outcome for breast cancer patients." (PMID 33801244, 2021). "Indeed, breast cancer cells exhibit increased autophagosomes-accumulation, MAP1LC3B-II/LC3B-II-conversion, expression of ATG proteins as well as elevated fusion of autophagosomes and lysosomes upon HNK treatment." (PMID 32963809, 2020). "Furthermore, breast cancer database analysis of 35 genes in the canonical autophagy pathway shows that the upregulation of ATG12 and MAP1LC3B is associated with a low relapse-free survival probability of patients with ERBB2-positive breast tumors following treatments." (PMID 33801244, 2021). "Accumulated protein levels of MAP1LC3B and SQSTM1 in treated breast cancer cell lines were observed and quantified." (PMID 34829743, 2021). "In addition, the accumulated MAP1LC3B and SQSTM1 proteins in breast cancer cell lines treated with autophagy inhibitors and their role in chemoresistance of breast cancer cell lines are studied." (PMID 34829743, 2021). "The accumulation of MAP1LC3B and SQSTM1 resulting from autophagy defects could facilitate chemosensitivity in breast cancer cell lines." (PMID 34829743, 2021). "Notably, stratification of breast cancer patients based on PNKP expression levels revealed a negative correlation between PNKP and MAP1LC3B, which encodes the LC3B autophagy protein." (PMID 40743845, 2025). "Thus, 1,25-(OH)2D3 and its analogues de-repress the key autophagic MAP1LC3B (LC3B) gene and activate 5′-AMP-activated protein kinase (AMPK) via increased cytosolic Ca2+ and activation of Ca2+/calmodulin-dependent protein kinase β in breast carcinoma cells." (PMID 35406059, 2022). "However, the biological role and clinical significance of MAP1LC3B and SQSTM1 in breast cancer remains unclear." (PMID 34829743, 2021). "Astonishingly, the autophagy inhibitor accumulated the protein levels of MAP1LC3B/SQSTM1 and enhanced the cytotoxic effects of cisplatin and paclitaxel in MCF7 and BT474 breast cancer cell lines, implying that autophagy inhibition might result in poor prognosis and chemosensitivity in IDC." (PMID 34829743, 2021). "Moreover, we found that MAP1LC3B and SQSTM1 might be accumulated due to autophagy inhibition in breast cancer cell lines." (PMID 34829743, 2021). "However, little is known about the role MAP1LC3B and SQSTM1 co-expression plays in breast cancer." (PMID 34829743, 2021). "Furthermore, we analyzed 35 autophagy genes involved in the classical autophagy pathway and found that ATG12 and MAP1LC3B are the only genes which upregulation is correlated with worse RFS-based survival probability in patients with ERBB2-positive but not ERBB2-negative breast cancer." (PMID 33801244, 2021). "However, the roles of MAP1LC3B and SQSTM1 in breast cancer are still not clear." (PMID 34829743, 2021).
gastric cancer (32 papers, 2012 to 2025). A primary or metastatic malignant neoplasm involving the stomach. "A previous study suggested that low MAP1LC3B expression was linked to poor prognosis in gastric cancer." (PMID 34707562, 2021). "The differential enrichment patterns observed for CTH and MAP1LC3B suggest their unique contributions to the molecular dynamics of gastric cancer, potentially offering avenues for targeted therapeutic strategies." (PMID 38388661, 2024). "In the human protein atlas, MAP1LC3B is labelled as a prognostic marker for renal and stomach cancer among the three shortlisted OGs." (PMID 34997044, 2022). "High MAP1LC3B expression is correlated with poor survival of patients with gastric cancer, OSCC and other disease." (PMID 34829743, 2021). "Elevated MAP1LC3B expression aligns with worse outcomes in gastric cancer patients." (PMID 38240686, 2024). "The dysregulation of Cystathionine Gamma-Lyase (CTH), Microtubule Associated Protein 1 Light Chain 3 Beta (MAP1LC3B), and monocyte-macrophage dynamics are critical determinants of the poor prognosis associated with gastric cancer (GC)." (PMID 38388661, 2024). "Immunohistochemistry analysis has identified an elevated staining intensity for autophagy related proteins such as Beclin1, Atg5, Atg8/ MAP1LC3B, and SQSTM1/p62 in gastric cancer tissue." (PMID 28109268, 2017).
lung carcinoma (30 papers, 2014 to 2025). "Notably, cachexia can be mediated by autophagy in lung cancer patients where BCL2 adenovirus E1B 19-kDa-interacting protein 3 (BNIP3) and Microtubule Associated Protein 1 Light Chain 3 Beta (LC3B) are the major players." (PMID 35441960, 2022). "Correlation analysis using the cancer tool suggests that FTH1 has a positive correlation with MAP1LC3B and pro-apoptotic protein BAX, whereas it is negatively correlated with the anti-apoptotic protein Bcl2 in lung carcinoma." (PMID 40538534, 2025). "MEN1-KD also inhibited the mRNA levels of ATG5, SQSTM1, and MAP1LC3B and decreased the protein levels of P62 and LC3B-II in another lung cancer cells (p < 0.05)." (PMID 40057469, 2025).
glioblastoma (25 papers, 2015 to 2026). The most malignant astrocytic tumor (WHO grade IV). "In human glioblastoma and several adenocarcinoma cell lines, it was shown that ER stress downstream of hypoxia results in transcriptional up-regulation of MAP1LC3B (LC3B) and ATG5, via ATF4 and CHOP." (PMID 29233873, 2017). "HiChIP data indicated increased chromatin interactions near MAP1LC3B and CHAC1 loci in ferroptotic glioblastoma cells." (PMID 37834393, 2023). "LN18 glioblastoma cells transduced by adenovirus expressing GFP-tagged NOP53 (Ad-NOP53) or control GFP (Ad-GFP) were starved in Earle’s Balanced Salt Solution (EBSS) medium or treated with rapamycin, and the number of MAP1LC3B (LC3B)-positive cells were counted as an indicator of autophagosomes." (PMID 34502226, 2021).
Sepsis (24 papers, 2012 to 2025). Sepsis is defined as life-threatening organ dysfunction caused by a dysregulated host response to infection. "In addition, the association between MAP1LC3B and sepsis has been increasingly revealed in recent years." (PMID 37861563, 2023). "Our results indicate that MAP1LC3B was significantly upregulated in the neutrophil of patients with sepsis when compared to that in control patients." (PMID 37861563, 2023). "We discovered that MAP1LC3B was significantly upregulated in the neutrophils of patients with sepsis when compared to control patients." (PMID 37861563, 2023). "To further verify the association between MAP1LC3B expression and neutrophils infiltration during sepsis, we used the GSE64457 dataset for the validation analysis as it contains neutrophil gene expression information for patients with sepsis and control patients." (PMID 37861563, 2023). "Notably, the expression patterns of core PCD-related genes in this cohort were highly consistent with those observed in the discovery datasets, with genes such as CYBB, GCLM, MAP1LC3B, NCKAP1, and PGD markedly upregulated in sepsis patients." (PMID 41346577, 2025).
colorectal cancer (23 papers, 2012 to 2025). A primary or metastatic malignant neoplasm that affects the colon or rectum. "In a study of ischemic stroke, MAP1LC3B was identified as a diagnostic marker for ischemic stroke and was highly expressed in the disease group, and MAP1LC3B was also found to be a potential biomarker for docosahexaenoic acid sensitivity in colorectal cancer cells." (PMID 37953920, 2023). "TRAF6 binds to MAP1LC3B/LC3B and induces LC3B K63-linked ubiquitination, which inhibiting colorectal cancer metastasis via regulating degradation of β-catenin by selective autophagy." (PMID 36202787, 2022). "Moreover, human colorectal cancer cells were treated with fruit extracts in the presence or absence of the autophagy inhibitor BafA1, followed by measurement of MAP1LC3B flux to reflect autophagy activity." (PMID 31159487, 2019).
melanoma (22 papers, 2016 to 2026). A malignant, usually aggressive tumor composed of atypical, neoplastic melanocytes. "Forced expression of microtubule-associated protein 1 light chain 3 beta (MAP1LC3B, encoding an autophagy initiator) restored the susceptibility of phosphatase and tensin homolog (PTEN)-deficient melanoma cells to T-cell-mediated cell killing." (PMID 38336727, 2024). "Moreover, we demonstrate that tumor-relevant genes, such as FosB, WEE1, PVR, MAP1LC3B, and LGALS3, are deregulated in melanoma by direct regulation via c-Jun5." (PMID 31378787, 2019).
ovarian carcinoma (21 papers, 2010 to 2025). A malignant neoplasm originating from the surface ovarian epithelium. "Knocking down BECN1 and microtubule-associated protein 1 light chain 3 beta (MAP1LC3B/LC3B), two frequently deleted autophagy genes in ovarian cancer, led to genomic instability and increased migration rates in atypical ovarian cancer cells." (PMID 38398197, 2024). "The upper part of the oncoprint shows that only 6% of ovarian cancer patients display genetic alterations in MAP1LC3B." (PMID 40497941, 2025). "Notably, we found that a low NKX3-2/high MAP1LC3B signature predicts a better prognosis for ovarian cancer patients." (PMID 40497941, 2025). "Remarkably, we observed that patients bearing a tumor with low NKX3-2 together with high MAP1LC3B levels (indicative of active autophagy) display a favorable clinical outcome, reinforcing the view that this signature may have translational relevance for ovarian cancer." (PMID 40497941, 2025). "We observed that MAP1LC3B was inversely correlated with IL6R and SLC2A1 mRNA expression in ovarian cancer patients TCGA data set." (PMID 36675246, 2023).
colon carcinoma (18 papers, 2013 to 2025). "MAP1LC3B-II and SQSTM1 dot-like staining are shown in tissues and are associated with a poor prognosis in patients with colon cancer." (PMID 30477228, 2018).
prostate carcinoma (17 papers, 2011 to 2025). A carcinoma that arises from epithelial cells of the prostate gland. "Three SNPs, ATG16L1 rs78835907, ATG16L1 rs13021297, and MAP1LC3B rs8044820, remained significant, and were selected to replicate findings in advanced prostate cancer cohort." (PMID 26365175, 2015).
viral infection (17 papers, 2015 to 2025). "Supporting a role for phagosome biogenesis and LAP in VAPA, the expression of genes involved in LAP, namely MAP1LC3B (microtubule-associated protein 1 light chain 3 beta) and SQSTM1 (sequestosome-1), was decreased in IAPA and CAPA compared to patients with viral infection alone." (PMID 38651925, 2024).
oral squamous cell carcinoma (11 papers, 2017 to 2025). "Studies have shown that MAP1LC3B and its adaptor sequestosome 1 (SQSTM1) modulate autophagy for tumorigenesis and prognosis in certain subsites of oral squamous cell carcinoma." (PMID 38240686, 2024).
emphysema (9 papers, 2013 to 2025). "Knockout of MMP-1, MMP12, neutrophil elastase (NE), IL-18Ra, TNFR-α, microtubule associated protein 1 light chain 3 beta (LC3B), nuclear factor erythroid-2-related factor 2 (Nrf2), and overexpression of CuZn superoxide dismutase can protect against CS-induced emphysema and inflammation." (PMID 38474149, 2024).
neuroblastoma (8 papers, 2014 to 2025). Neuroblastoma (NB) is the most common solid, extracranial childhood tumor. "While ABT-199 successfully induces apoptosis in high BCL2-expressing neuroblastoma SHSY-5Y cells, BAU-243 triggered autophagic cell death rather than apoptosis in GBM A172 cells, indicated by the upregulation of BECN1, ATG5, and MAP1LC3B expression." (PMID 36309485, 2022).
ischemic stroke (7 papers, 2020 to 2025). A stroke disorder caused by obstruction of blood flow to the brain, due to thrombotic (local blood clot formation) or embolic (due to a blood clot or other material traveling from another site) event. "All in all, our results suggested MAP1LC3B, PTGS2, and TLR4 as potential diagnostic biomarkers for ischemic stroke, providing more evidence about the vital role of ferroptosis in ischemic stroke." (PMID 34707562, 2021). "The expression and diagnostic value of MAP1LC3B, PTGS2, and TLR4 in ischemic stroke were also verified using GSE22255." (PMID 34707562, 2021). "By the bioinformatic analysis, three ferroptosis-related biomarkers are found as potential diagnostic biomarkers for ischemic stroke, namely, PTGS2, MAP1LC3B, and TLR4, which are upregulated in ischemic stroke and provide more evidence about the important role of ferroptosis." (PMID 35264947, 2021). "Moreover, the ROC diagnostic accuracy of MAP1LC3B, PTGS2, and TLR4 was 71.75, 68.26, and 53.25%, respectively, further confirming the diagnostic value of three ferroptosis-related biomarkers in ischemic stroke." (PMID 34707562, 2021). "By constructing a random forest model and performing ROC monofactor analysis, we identified three ferroptosis-related biomarkers, namely, MAP1LC3B, PTGS2, and TLR4, for ischemic stroke." (PMID 34707562, 2021). "As a result, the accuracy of MAP1LC3B, PTGS2, and TLR4 in the diagnosis of ischemic stroke was 67.74, 72.86, and 74.25, respectively, in the GSE16561 dataset." (PMID 34707562, 2021). "The expression of three other ferroptosis-related biomarkers, PTGS2, MAP1LC3B, and TLR4, was all upregulated in ischemic stroke patients vs. normal control in the GSE16561 (all p < 0.05) and GSE140275 datasets (all p < 0.05)." (PMID 34707562, 2021). "Moreover, the random forest model suggested three ferroptosis-related biomarkers, namely, PTGS2, MAP1LC3B, and TLR4, for ischemic stroke." (PMID 34707562, 2021). "Actually, a previous study had reported that MAP1LC3B, PTGS2, and TLR4 may play a vital role in ischemic stroke or served as biomarkers for ischemic stroke and other diseases." (PMID 34707562, 2021). "Interestingly, the expression of PTGS2, MAP1LC3B, and TLR4 was upregulated in ischemic stroke." (PMID 34707562, 2021). "Finally, the non-cooperatively expressed MIF was removed, and PTGS2, MAP1LC3B, and TLR4 were further selected as ferroptosis-related biomarkers for ischemic stroke." (PMID 34707562, 2021).
triple-negative breast carcinoma (7 papers, 2017 to 2025). An invasive breast carcinoma which is negative for expression of estrogen receptor (ER), progesterone receptor (PR), and human epidermal growth factor receptor 2 (HER2). "Regarding individual gene expression, a high expression of MAP1LC3B (usually called LC3B) has been associated to poor prognosis in triple negative breast cancer TNBC." (PMID 33488952, 2020).
Cachexia (6 papers, 2011 to 2024). Severe weight loss, wasting of muscle, loss of appetite, and general debility related to a chronic disease. "The expression levels of mitophagy-related proteins, such as microtubule-associated protein 1 light chain 3 beta (MAP1LC3β), Parkin, PTEN induced kinase 1 (PINK1), and BCL2 interacting protein 3 (BNIP3), are altered in cachexia." (PMID 36361713, 2022).